IL13RA2 (interleukin 13 receptor subunit alpha 2)
Diseases named in the same sentence as IL13RA2 in open-access papers (continued):
Sharing a sentence is not in itself a finding about the gene and the disease.
tumor (308 papers, 2007 to 2026). "In this context, current approaches include the assessment of CAR T cells targeting tumor-associated antigens such as IL-13Rα2 and EGFRvIII, as well as inhibitors of PD-1/PD-L1 axis." (PMID 41514664, 2026). "CAR-T cells engineered to target specific GBM antigens, such as epidermal growth factor receptor variant III (EGFRvIII) and interleukin-13 receptor alpha 2 (IL13Rα2), have shown potent anti-tumor activity in vitro and in vivo." (PMID 40223940, 2025). "In conclusion, this study indicates that IL13RA2 deficiency promotes tumor cell survival, growth, and metastasis in models of brain-metastatic TNBC." (PMID 40663259, 2025). "B7-H3 (CD276), an immune checkpoint molecule involved in tumor progression, along with receptors EGFRvIII and IL13Rα2, are highly overexpressed in GBM and associated with worse prognoses, making them attractive therapeutic targets." (PMID 39941829, 2025). "Both IL13RA2-deficient models demonstrate enhanced cell survival in vitro, as well as augmented metastatic tumor growth and worsened animal survival in intracardiac models of brain metastasis." (PMID 40663259, 2025). "Here, we discuss several tumor antigens, such as interleukin-13 receptor subunit alpha 2 (IL-13Rα2) and epidermal growth factor receptor variant III (EGFRvIII), that have been targeted to develop CAR-T-cell therapies for GBM treatment." (PMID 39406966, 2024). "A multivariate analysis was conducted, including age, tumor size, stage, T and M categories, and IL-13Rα2 expression, all of which were significantly associated with OS or RFS in the univariate analysis." (PMID 39598436, 2024). "De novo engineered T cells are currently under clinical study in GBM, including the targeting of the tumor-associated antigens IL13Rα2, HER2, and EGFRvIII (NCT04003649, NCT03696030, and NCT02664363)." (PMID 38994929, 2024). "This was followed by a case study they published the following year, with the administration of CAR-modified T cells targeting the tumor-associated antigen IL13Rα2 to a patient with recurrent multifocal GBM." (PMID 37304305, 2023). "There remains limited understanding of how IL13-ligand CAR design impacts the activity and selectivity for the intended tumor-associated target IL13Rα2 versus the more ubiquitous unintended target IL13Rα1." (PMID 36968221, 2023). "A short remission was observed in one patient, possibly due to IL-13Rα2 antigen loss on the relapsing tumor." (PMID 36717905, 2023). "Both expression level of IL-13Rα2 and IL-13Rα2-mediated signaling has been reported to cause cell survival, tumor proliferation, tumor progression, invasion, and metastasis." (PMID 37176567, 2023). "The herein presented findings in HGG xenograft models with low, medium and high IL-13Rα2 levels demonstrate that GB-13 decreases tumor volume and prolongs survival in a manner strongly associated with IL-13Rα2 status." (PMID 35631512, 2022). "The purpose of this study was to determine the impact of tumor-associated IL-13Rα2 levels on the therapeutic efficacy of IL-13Rα2-targeted therapy in HGG." (PMID 35631512, 2022). "While the exact cause of relapse remains to be elucidated, instances of tumor recurrence with loss and/or reduced expression of IL13Rα2 has been observed." (PMID 35428347, 2022). "High expression of IL-13Rα2 was also associated with higher tumor stages and poor outcome in human CRC patients." (PMID 33450900, 2021). "In this cut-off value, IL13Rα2-positivity was significantly associated with tumor size (P = 0.004), tumor stage (P = 0.002), histologic nuclear grade of tumor cells (P < 0.001), and histologic subtype of RCC (P = 0.005) in 229 cases of RCCs." (PMID 33917914, 2021). "As required for tumor-associated targets, IL13Ra2 is highly expressed in a high frequency on tumor cells of GBM patients." (PMID 34884607, 2021).
tumor (continued). "In CCRCC subgroup, IL13Rα2-positivity was significantly associated with tumor size (P = 0.005), tumor stage (P = 0.003), and histologic nuclear grade of tumor cells (P < 0.001)." (PMID 33917914, 2021). "High expression of IL-13Rα2 in ACC tumor samples resulted in a low survival rate and associated with tumor reoccurrence and excess hormone production." (PMID 33591997, 2021). "In CRC, a statistically significant association was observed between IL13Rα2 expression and tumor progression (T stage), with higher expression in T3 or T4 tumors as compared with T1 or T2." (PMID 32098194, 2020). "The overexpression of IL-13Rα2 in lung ECs significantly increased the tumorigenic, migratory and angiogenic properties of cells, suggesting that IL-13Rα2 promotes the malignant transformation of lung ECs and genesis of tumor-associated ECs." (PMID 31205749, 2019). "IL-13Rα1 and IL-13Rα2 are known tumor-associated antigens and recent clinical trials have explored inoculation with IL-13Rα2 and other tumor associated antigens as an immunotherapy." (PMID 29621254, 2018). "IL-13 and IL-4 modify the function of macrophages, and IL13RA2 mediates IL13/4 mediated tumor associated macrophage M1/M2-Th1/Th2 phenotype, especially, IL-13 signaling promote to change M1 to M2." (PMID 26114873, 2015). "A previous study reported that higher expression of IL13RA2 was associated with tumor progression of certain types of cancer." (PMID 26114873, 2015). "Instead of exposing the cells to lysates, which offer complex cocktail of different antigens, more targeted immune response can be affected by pulsation of the dendritic cells with purified tumor-associated peptides such as IL13Rα2, EGFRvIII, or gp100." (PMID 25247196, 2014). "Higher expression of IL-13Rα2 is therefore primarily limited to the tumor cells and does not appear to be aberrantly triggered in any other tissues through the tumor induction process, which causes conditional deletion of TGFβRI and PTEN." (PMID 23421960, 2013). "The expression of IL-13Rα2 has been linked to deleterious immune effect such as tumor immune evasion, particularly since signaling through this receptor causes upregulation of the immunosuppressive cytokine TGF-β1." (PMID 23421960, 2013). "These T and B cell responses induced by prime-boost strategy correlated with tumor responses causing reduced tumor burden and significantly prolonging mice survival, compared with the IL-13Rα2 DNA vaccine alone." (PMID 21067607, 2010). "Previous studies have shown that interleukin-13 receptor α2 chain (IL-13Rα2), a tumor-associated antigen is a promising target for cancer immunotherapy as high levels of IL-13Rα2 are expressed on a variety of human tumors." (PMID 21067607, 2010). "It would also be intriguing to delineate molecular mechanisms underlying the antigen presentation against EphA2- and IL-13Rα 2-derived epitopes in the patient AA-1 that led to anti-tumor immunity instead of tolerance." (PMID 18093336, 2007). "We evaluated expression of IL-13Rα2 and EphA2 in tumor tissues derived from the patient AA-1, as these GAAs encode well characterized HLA-A2-restricted CTL epitopes." (PMID 18093336, 2007). "Additionally, IL13RA2 expression was positively correlated with nonsynonymous somatic mutation count, suggesting a possible association with tumor immunogenicity or genomic instability." (PMID 40855097, 2025). "However, other reports suggest that elevated IL13RA2 in tumor cells or cancer-associated fibroblasts correlates with improved patient survival." (PMID 40663259, 2025). "Notably, a positive correlation has been observed between higher IL13Rα2 expression tumor grade and it serves as a prognostic marker associated with poor patient survival." (PMID 41268299, 2025). "In addition, IL‐13Rα2 is associated with tumour progression and invasion leading to poor prognosis of subjects with IL‐13Rα2 overexpressing tumours." (PMID 38685487, 2024).
tumor (continued). "Although one patient experienced brief remission, it may have been attributed to the loss of the IL-13Rα2 antigen on the relapsing tumor." (PMID 39335671, 2024). "The expression of IL13Rα2 is often associated with invasion, metastasis, and advanced stage in tumor cells; therefore, this receptor has the potential to be considered for tumor-specific therapeutics." (PMID 39118800, 2024). "It is also reported that IL‐13Rα2 gene belongs to the top 10% of 73 evaluated tumour‐associated antigens analysed by Nanostring digital RNA counting that were differentially expressed between tumours and normal tissues." (PMID 38685487, 2024). "Notably, the most common tumour-associated antigens are EGFRvIII and interleukin 13-receptor α 2 (IL-13Rα2)." (PMID 38615034, 2024). "Moreover, rGBMs post IL13Rα2-CAR T cells therapy resulted in IL13Rα2 antigen loss GBM variants that increased the tumor survival and proliferation." (PMID 37275361, 2023). "Each of the IL13(E12Y)-CAR T cell variants were also able to efficiently kill IL13Rα2-expressing tumor cells in a 48-hour coculture at E:T ratios of 1:4, although the third-generation IL13-28BBζ CAR displayed slightly reduced killing potency against the GBM line PBT030-2." (PMID 36968221, 2023). "Using a more stringent E:T ratio of 1:10 showed uniform differences in cytotoxic activity for all CAR T cell variants across antigen expression levels, with all variants killing higher percentages of tumor cells with higher IL13Rα2 expression levels (P < 0.0001 for all comparisons)." (PMID 35939683, 2022). "Unfortunately, in this trial, one patient experienced shorter remission, which may be related to the loss of IL13Rα2 antigen on the relapsed tumor, leading to the poor response of IL13Rα2 CAR-T cells against GBM." (PMID 36261831, 2022). "Therefore, we searched the TCGA database for possible mutations in the sequence of the IL-13Rα2 gene from ACC tumor samples." (PMID 33591997, 2021). "Unfortunately, disease recurrence was observed after 7.5 months with tumor formation in new locations and decreased expression of IL13Rα2, elucidating a common antigen loss response to targeted therapies and advocating for rational combinational or adjuvant therapies." (PMID 34298615, 2021). "In addition, high IL-13Rα2 expression was significantly associated with a higher incidence of new tumor events and excess hormone production compared to low or medium IL-13Rα2 expression." (PMID 33591997, 2021). "Furthermore, expression of amphiregulin promoted tumour growth, implicating causal relationship between the expression of IL13Rα2 and amphiregulin." (PMID 30718742, 2019). "Since we found that increased level of IL13Rα2 expression in the SK-MEL-28 cells promoted in vivo tumorigenicity and angiogenesis, we next questioned whether loss of endogenous IL13Rα2 expression in A375 cells would affect in vivo tumour growth." (PMID 30718742, 2019). "Also, the abundance of IL-13Rα2 on glioblastoma cells was clinically explored by designing an IL-13-linked toxin to kill tumor cells in a phase I clinical trial." (PMID 30759882, 2019). "However, the authors noted that residual tumor tissue adjacent to the site of injection displayed significantly lower expression of IL13Rα2, implying antigen loss as a result of therapy." (PMID 30740109, 2018). "In addition to demonstrating tumor targeting and therapeutic potential of Pep-1L, we also developed a translational companion diagnostic that can be used to demonstrate real-time IL13RA2 expression in tumors." (PMID 28881623, 2017). "Interleukin-13 Receptor α2 (IL-13Rα2) is a tumor-associated antigen and target for cancer therapy." (PMID 21477288, 2011). "We have extended our prior studies and hypothesized that immunization with a DNA vaccine encoding murine IL-13Rα2, boosted with ECDα2 protein, may work more effectively in syngeneic murine tumor models." (PMID 21067607, 2010).
tumor (continued). "Currently, CAR-T immunotherapy targeting IL13Ra2 are being research as the target is a commonly expressed membrane-bound protein in over three-quarters of GBMs and is associated with activating the mTOR (mammalian target of rapamycin) pathway, which favours tumour growth." (PMID 36299480, 2022). "We developed a fully humanized BTE (hBTE) targeting interleukin-13 receptor alpha 2 (IL13RA2), a tumor-associated antigen widely expressed in GBM and associated with poor prognosis." (PMID 42057694, 2026). "Secreted by tumor-associated astrocytes, chitinase 3-like 1 (CHI3L1) binds to IL-13 receptor alpha 2 (IL-13Rα2) on the tumor cell surface." (PMID 40345526, 2025). "For instance, compared to single-antigen CAR T-cells, dual-targeted CAR T-cells that recognize both EGFRvIII and IL-13Rα2 have demonstrated improved antitumor effectiveness because they can eradicate a variety of tumor cell types." (PMID 40585996, 2025). "Shifting from tumor-intrinsic receptor targeting to mobilizing adaptive immunity, BsAbs that engage IL-13Rα2 on tumor cells and CD3 on T cells open a distinct therapeutic avenue." (PMID 41209565, 2025). "This tumor-specific expression pattern has attracted interest in IL-13Rα2 as a promising target for cancer immunotherapy." (PMID 40855097, 2025). "Conversely, IL13Rα2 exhibited diffuse staining patterns across tumor cells, suggesting widespread expression in the neoplasm." (PMID 40855097, 2025). "A recent study in GBM found that high levels of IL13RA2 in patient plasma or tumor samples predicted improved survival." (PMID 40663259, 2025). "For instance, CRISPR-Cas9-mediated knockout of PD-1 in CAR-T cells targeting IL13Rα2 resulted in increased T-cell persistence and anti-tumor activity in GBM models." (PMID 40223940, 2025). "Given that the B7‐H3 and IL‐13Rα2 combination shows higher coverage than other combinations across different patient tumor samples, this combination has a certain level of general applicability." (PMID 40112194, 2025). "Through the analysis of different tumor samples, we found that combinations of dual‐target antigens, such as B7‐H3 and IL‐13Rα2, can cover more than 80% of tumor regions." (PMID 40112194, 2025). "There is substantial interest in exploiting tumor-specific IL13RA2 for either payload targeting or direct inhibition." (PMID 40663259, 2025). "This conclusion was supported by the finding that CHI3L1-driven metastasis was dramatically reduced in IL-13Rα2 KO mice, confirming that IL-13Rα2 is essential for CHI3L1-mediated tumor progression in this model." (PMID 40643503, 2025). "Once across the BBB, tumor specificity is achieved through ligands targeting overexpressed receptors such as EGFRvIII, IL13Rα2, and CD44." (PMID 40944840, 2025). "In parallel, adaptive T cell therapies such as IL13Rα2-targeted chimeric antigen receptor (CAR) T cells are also gaining attention owing to their effectiveness against tumor growth in glioma and other tumor models." (PMID 41268299, 2025). "IL-13 interacts with its high-affinity receptor IL-13Rα2, inhibiting tumor cell apoptosis and resulting in poor tumor prognosis." (PMID 39934258, 2025). "IL-13Rα2 is overexpressed in the majority of glioblastomas but is essentially absent from normal brain tissue, making it an almost tumor-exclusive marker." (PMID 40918539, 2025). "CHI3L1 induces M2-type macrophages through the IL-13Rα2-mediated signaling cascade; in turn, these macrophages promote tumor cell proliferation, immunosuppression, and angiogenesis." (PMID 40643503, 2025). "The IVIS Spectrum revealed that the treatment group with double CAR‐Vδ1 T cells exhibited a faster tumor regression effect, significantly higher than the single B7‐H3 or IL‐13Rα2 CAR‐Vδ1 T cell group." (PMID 40112194, 2025). "Post-infusion histopathologic analysis of resected tumor tissue revealed reduced expression of IL13Rα2 and EGFRvIII in both patients, respectively." (PMID 39941829, 2025).
tumor (continued). "This involves engineering autologous T cells to express receptors targeting tumor-specific antigens such as IL13Rα2, EGFRvIII, or HER2, and reinfusing them into the patient." (PMID 40650289, 2025). "B7‐H3, IL‐13Rα2, and Her2 expression levels were inconsistent within different regions even in the same tumor." (PMID 40112194, 2025). "It systematically evaluates the results of studies targeting key tumor-associated antigens, such as EGFR, IL13Rα2, GD2, B7-H3, CEA, MSLN, PSCA/PSMA, and ROR1." (PMID 40969260, 2025). "Although two patients saw a temporary decrease in GMB activity, analysis of tumor tissue from one patient revealed a drop in total IL13Rα2 expression." (PMID 40585996, 2025). "We show that IL13RA2 deletion promotes cancer cell proliferation and survival in vitro and enhances tumor cell metastasis in vivo." (PMID 40663259, 2025). "Given the complex and context-dependent roles of IL13RA2, it is important to understand its biological role within a specific tumor type before manipulating its activity." (PMID 40663259, 2025). "Tumor inter‐ and intra‐heterogeneity was confirmed for target gene expression (B7‐H3, IL‐13Rα2) in corresponding GBOs through immunofluorescence." (PMID 40112194, 2025). "Dual CAR T cells targeting both HER2 and IL13Rα2 have demonstrated improved tumor control and delayed progression compared to single-target CAR T-cell approaches." (PMID 40868217, 2025). "It is worth noting that radiolabeling has negligible effects on the biological properties of CAR T cells, specifically in terms of their effectiveness in targeting IL-13Rα2-positive tumor cells." (PMID 38730680, 2024). "Two patients experienced transient anti-glioma responses, with one patient showing decreased IL13Rα2 expression in tumour tissue after treatment and the other exhibiting an increase in tumour necrosis volume at the administration site on MRI." (PMID 38660136, 2024). "IL13Rα2, a high affinity IL-13 receptor monomer expressed by myeloid-derived suppressor cells and tumour-infiltrating macrophages, in over 50% of GBMs, has been associated with poor survival." (PMID 38660136, 2024). "In in vivo models, both types of IL-13Rα2 CAR-T cells inhibited tumor growth and prolonged the survival of mice." (PMID 38339374, 2024). "In contrast, overexpression of IL-13Rα2 significantly increased tumor growth under treatment with doxorubicin." (PMID 39598436, 2024). "Our ongoing studies will address the possibility that our newly engineered anti‐IL‐13 Rα2 construct will improve tumour specificity and reduce potential for off target effects due to expression of IL‐13 Rα1 on normal tissues." (PMID 38685487, 2024). "In order to avoid recruitment difficulties in the bloodstream, another approach involves directly infusing CAR IL-13Rα2 into the tumor by intralesional or intrathecal infusion." (PMID 38932383, 2024). "Tumor-derived cell lines derived express IL13RA2 and reliably developed tumors when implanted orthotopically in the murine brain." (PMID 39711568, 2024). "When two oncoproteins (EGFRvIII and IL-13Rα2) are expressed, an increased EGFRvIII tyrosine kinase activity is observed, which results in tumor growth." (PMID 38339374, 2024). "In vitro, both types of CAR-T cells inhibited tumor cell growth, with m-IL-13Rα2 CAR-T cells releasing higher levels of IFN-γ and IL-6 compared to h-IL-13Rα2 CAR-T cells." (PMID 38339374, 2024). "In particular, only one patient demonstrated a complete response to IL-13Rα2-targeting CAR T-cell therapy before tumour recurrence." (PMID 38615034, 2024). "The differential expression of IL-13Rα2 in normal versus tumor tissue, coupled with the receptor’s role in facilitating tumor growth, survival, invasion, and metastasis through IL-13Rα2-mediated signaling, underscores its potential as a therapeutic target." (PMID 38612592, 2024).